RBP4 (retinol binding protein 4)
Description:
Retinol-binding protein that mediates retinol transport in blood plasma. Delivers retinol from the liver stores to the peripheral tissues (Probable). Transfers the bound all-trans retinol to STRA6, that then facilitates retinol transport across the cell membrane.
Synonyms: MCOPCB10; RDCCAS
Tractability: Small molecule: a structure with a bound ligand is known; a high-quality ligand is known; it has a high-quality binding pocket; it belongs to a druggable protein family. Antibody: UniProt places it where antibodies can reach, with high confidence; its Gene Ontology location is reachable by antibodies, with high confidence; UniProt predicts a signal peptide or a membrane-spanning region. PROTAC: its protein half-life has been measured; a small molecule that binds it is known.
Target class: Secreted protein
Gene: Protein-coding gene on chromosome 10 (93,590,170 to 93,603,110, reverse strand). Ensembl gene ENSG00000138207.
Subcellular location: Secreted
Pathways (Reactome):
Disease: Defective visual phototransduction due to STRA6 loss of function; Retinoid metabolism disease events
Sensory Perception: Retinoid metabolism and transport; The canonical retinoid cycle in rods (twilight vision)
Gene Ontology:
Molecular function: protein binding; retinol binding; all-trans-retinol binding; retinol transmembrane transporter activity; molecular carrier activity; protein-containing complex binding; retinoid binding
Biological process: eye development; gluconeogenesis; glucose homeostasis; maintenance of gastrointestinal epithelium; positive regulation of insulin secretion; response to retinoic acid; retinol metabolic process; cardiac muscle tissue development; embryonic organ morphogenesis; embryonic retina morphogenesis in camera-type eye; embryonic skeletal system development; female genitalia morphogenesis; heart development; heart trabecula formation; lung development; negative regulation of cardiac muscle cell proliferation; positive regulation of immunoglobulin production; retinoid metabolic process; retinol transport; urinary bladder development; uterus development; vagina development; response to ethanol; response to muscle activity; response to xenobiotic stimulus
Cellular component: extracellular exosome; extracellular region; protein-containing complex
Genetic constraint (gnomAD): Loss-of-function variants: 9 observed, 27.32 expected, observed/expected ratio (o/e) 0.33, 90% interval 0.2 to 0.57. The upper end of that interval is the gene's LOEUF score, 0.57, which puts it in group 2 of 6, group 1 being the genes least tolerant of losing a copy. Missense variants: 236 observed, 275.41 expected, observed/expected ratio (o/e) 0.86, 90% interval 0.77 to 0.95. Synonymous variants: 108 observed, 114.89 expected, observed/expected ratio (o/e) 0.94, 90% interval 0.8 to 1.1.
Gene-disease validity (ClinGen):
ClinGen rates the evidence that RBP4 causes each of these diseases.
progressive retinal dystrophy due to retinol transport defect (autosomal recessive): Definitive.
Homologues: Orthologues: chimpanzee RBP4 (100% identical), macaque RBP4 (99% identical), pig RBP4 (92% identical), mouse Rbp4 (86% identical), rat Rbp4 (86% identical), dog RBP4 (84% identical), rabbit RBP4 (81% identical), guinea pig RBP4 (72% identical), tropical clawed frog rbp4 (58% identical), zebrafish rbp4 (56% identical).
Diseases named in the same sentence as RBP4 in open-access papers:
RBP4 is named in the same sentence as 293 diseases in open-access papers, as found by Europe PMC text mining. Sharing a sentence is not in itself a finding about the gene and the disease. The quoted sentences say what the papers report.
Insulin resistance (364 papers, 2008 to 2026). Increased resistance towards insulin, that is, diminished effectiveness of insulin in reducing blood glucose levels. "Retinol-binding protein 4 (RBP4), an adipokine secreted by adipose tissues, has been implicated in metabolic inflammation and insulin resistance." (PMID 41744664, 2026). "RBP4 has been implicated in insulin resistance and chronic low-grade inflammation, both of which are recognized contributors to cancer development and progression." (PMID 41007818, 2025). "RBP4 generally is associated with deleterious effects, including increased insulin resistance, primarily by its ability to stimulate pro-inflammatory cytokines, thus contributing to the development of type 2 diabetes." (PMID 41515891, 2025). "Elevated serum RBP4 levels are associated with insulin resistance and T2DM, correlating with impaired glucose tolerance and hyperinsulinemia." (PMID 40276651, 2025). "Elevated levels of retinol-binding protein 4 (RBP4) have been linked to conditions including cardiovascular disease, type 2 diabetes, obesity, and insulin resistance." (PMID 40881125, 2025). "Beyond its role in vitamin A transport, RBP4 has been linked to insulin resistance since 2005, when research showed increased RBP4 levels in insulin-resistant mouse models and decreased susceptibility to insulin resistance in RBP4-deficient mice." (PMID 40951890, 2025). "A nested, retrospective cohort study provided evidence that increased RBP4 levels were associated with significantly greater odds of worsening insulin resistance and hypertriglyceridaemia in overweight, postpubertal, non-Hispanic black teenage participants." (PMID 38520616, 2024). "Beyond its established role in lipid metabolism, RBP4 is increasingly recognized for its association with insulin resistance." (PMID 39589965, 2024). "Elevated levels of circulating RBP4 have been linked to obesity, insulin resistance, impaired glucose tolerance, and T2DM in humans, according to a few studies." (PMID 38732128, 2024). "Taken together, the results of animal experiments, prospective studies, meta-analyses, genetic studies and intervention studies support the significant associations between RBP4 levels, insulin resistance, pancreatic β-cell function, and T2DM." (PMID 38520616, 2024). "High levels of RBP4 have been associated with inflammation in metabolic disorders like insulin resistance, metabolic syndrome, fatty liver, cardiovascular diseases like atherosclerosis, and chronic inflammatory diseases such as psoriasis." (PMID 38275649, 2024). "Retinol-binding protein 4 (RBP4), associated with insulin resistance, shows increased levels in GDM, with second-trimester measurements showing strong predictive performance (AUC 0.87)." (PMID 39519218, 2024). "A study using genetically modified mice showed that transgenic overexpression of RBP4 caused insulin resistance, whereas genetic deletion of RBP4 enhanced insulin sensitivity." (PMID 38672227, 2024). "Overall, there were significant associations between RBP4 levels, insulin resistance, pancreatic β-cell function, and T2DM." (PMID 38520616, 2024). "Cross-sectional studies have shown that elevated circulating RBP4 levels are strongly and independently associated with insulin resistance in the adult general population, perimenopausal women, and individuals with T2DM." (PMID 38520616, 2024). "Fenretinide, a ligand of RBP4, has been suggested to reduce insulin resistance and associated disorders, such as obesity and fatty liver disease, by reducing the serum RBP4 concentration." (PMID 38520616, 2024). "RBP4 is associated to cardiovascular risk, inflammation, and insulin resistance, all of which are involved in NAFLD." (PMID 37996653, 2024). "For type 2 diabetes, a common metabolic disorder associated with insulin resistance, an aptamer-based biosensor has been created for the quick detection of Retinol Binding Protein 4 (RBP4) levels in serum samples." (PMID 39685966, 2024).
Insulin resistance (continued). "A study found that exosomes mediate communication between adipocytes and macrophages in a spontaneously obese mouse model of leptin-deficient and that retinol-binding protein 4 (RBP4) stimulates macrophage activation and insulin resistance." (PMID 37981718, 2023). "They include the fatty acid binding protein 4 (FABP4), retinol-binding protein 4 (RBP4), and adiponectin, which have been associated with liver steatosis and insulin resistance." (PMID 38034016, 2023). "Retinol-binding protein 4 and haptoglobin protein were downregulated, which are associated with insulin resistance and inflammation, respectively." (PMID 36364802, 2022). "RBP4 is a reliable marker of insulin resistance, and is possibly associated with the onset mechanism of acute graft-versus-host disease (aGvHD) and/or skin GvHD." (PMID 35977993, 2022). "As a metabolic risk factor in obesity, RBP4 has been associated with insulin resistance and adipose accumulation." (PMID 36686076, 2022). "Retinol-binding protein 4 (RBP4) has been implicated in insulin resistance in rodents and humans with obesity and T2DM, making it a potential biomarker for the early diagnosis of T2DM." (PMID 36551028, 2022). "High serum RBP4 concentrations have been associated with dysregulation of energy metabolism, insulin resistance, diabetes mellitus and obesity." (PMID 35806431, 2022). "Retinol-binding protein 4 (RBP4), a retinol transporter in circulation belonging to the lipocalins family, has been reported to be associated with type 2 diabetes, obesity, insulin resistance, and other cardiometabolic disorders." (PMID 35634496, 2022). "RBP4 is considered independently related to insulin resistance, which is implicated in the pathogenesis of hyperuricemia." (PMID 35846279, 2022). "A study conducted on type 2 diabetes patients also demonstrated that serum RBP4 levels were associated with insulin resistance and severity of coronary artery disease." (PMID 35745841, 2022). "Both clinical and basic studies demonstrated that serum levels of RBP-4 were positively correlated with improved insulin resistance parameters and inversely associated with islet function." (PMID 35547000, 2022). "It is associated with low-grade and chronic inflammation, a physiological condition characterized by high concentrations of pro-inflammatory cytokines (e.g., RBP4, leptin, and IL-6) in tissues or the circulation and linked to insulin resistance." (PMID 35629362, 2022). "Although the cause of insulin resistance is not fully understood, it is thought to be associated with adipocytes inflammation induced by RBP4, iron overload and hemolytic anemia after HSCT, as observed in this study." (PMID 35977993, 2022). "The long-term HFHF diet further exacerbated the downregulation of Rbp4 (encoding retinol-binding protein 4, which is an adipokine involved in the development of obesity and insulin resistance) expression in beta cells compared to the age-matched group." (PMID 35683981, 2022). "RBP4 wasalso associated with the severity of insulin resistance in patients with obesity,impaired glucose tolerance, or DM." (PMID 39076230, 2022). "As a newly identified adipokine, RBP4 was suggested to be associated with the pathogenesis of insulin resistance and T2DM." (PMID 35082965, 2022). "The list included the novel adipocytokine Retinol Binding Protein 4 (RBP4) that is known to be associated with obesity, insulin resistance, and cardiovascular diseases." (PMID 35264099, 2022). "Although the cause of insulin resistance is not fully understood, it is thought to be associated with adipocytes inflammation induced by RBP4, iron overload and hemolytic anemia after hematopoietic stem cell transplantation." (PMID 35977993, 2022). "Other studies focusing on target organs have shown that overexpression of adipocyte-specific RBP4 increases the levels of pro-inflammatory markers and lipases associated with lipolysis, thereby promoting insulin resistance." (PMID 33679618, 2021).
Insulin resistance (continued). "Sex differences in the associations of circulating RBP4 concentrations with insulin resistance and fasting blood glucose levels have been reported." (PMID 34419052, 2021). "Adipocytes of CAD patients are characterized by an even more pronounced decrease in GLUT4 and an increased content of retinol-binding protein-4 (RBP4), associated with the development of insulin resistance." (PMID 33440802, 2021). "Retinol-binding protein 4 (RBP4), a new adipocytokine, participates in the pathological process of human insulin resistance and is associated with the lipid metabolism." (PMID 34422084, 2021). "Accordingly, we observe a significant increase in levels of Rbp4 RNA, encoding a transporter protein known to be upregulated in Glut4-null animals and contributing to insulin resistance in obese and T2D patients." (PMID 34707105, 2021). "Several human and animal studies have investigated the influence of high circulating RBP4 levels in the pathogenesis of insulin resistance associated with type 2 diabetes and obesity." (PMID 33716957, 2021). "RBP4, originally characterized as a transport protein for retinol to the tissue, is associated with lipid metabolism, and insulin resistance." (PMID 35145478, 2021). "We postulated that retinol-binding protein-4 is linked to insulin resistance and the severity of coronary artery disease." (PMID 34571734, 2021). "RBP4 is usually associated with obesity, type 2 diabetes mellitus and insulin resistance in most studies." (PMID 33235563, 2020). "Upregulated according to obesity, PSMB1 was transcriptional activator of RBP4 – a gene associated with insulin resistance and transcription activation of adipocyte." (PMID 32801562, 2020). "RBP4 is an adipokine that has been implicated in the pathophysiology of insulin resistance through immunity, inflammatory, and GLUT4 regulation mechanisms in adipose and vascular tissues." (PMID 32178221, 2020). "As a metabolic risk factor in obesity, RBP4 has been reported to be associated with insulin resistance and adipose accumulation." (PMID 31956345, 2020). "Comorbidities such as obesity, diabetes mellitus, and insulin resistance affect RBP4 levels, causing bias in detection." (PMID 31956331, 2020). "The occurrence of systemic insulin resistance is directly linked to an elevation in serum RBP4 that is secreted from adipose tissue." (PMID 32864980, 2020). "Upregulation of retinol-binding protein 4 (RBP4) in human blood serum is linked with insulin resistance, the development of T2DM, and such clinical manifestations of metabolic syndrome as obesity, glucose intolerance, dyslipidemia, and hypertension." (PMID 32121175, 2020). "Recent clinical studies in adults have demonstrated that RBP4 levels were associated with metabolic syndrome, obesity, insulin resistance, and type 2 DM (T2DM)." (PMID 33082885, 2020). "In human studies, RBP4 correlates with the magnitude of insulin resistance, and elevated RBP4 is associated with an increased risk of type 2 DM." (PMID 31921323, 2020). "A decrease in adipose tissue GLUT4 expression, which is the major glucose transporter protein mediating glucose uptake, leads to increased serum RBP4 levels associated with the induction of insulin resistance in the liver and muscle." (PMID 32718041, 2020). "As the research studies have demonstrated, RBP4 is associated with insulin resistance (IR), which is further associated with chronic subclinical inflammation and can promote vascular inflammation." (PMID 32718041, 2020). "Further research is needed to understand the underlying mechanism between RBP4 and insulin resistance during pregnancy." (PMID 31921323, 2020). "RBP4, which is involved in retinol metabolism, has also been identified to be associated with numerous metabolic diseases, such as insulin resistance (IR), type 2 diabetes mellitus, obesity, and cardiovascular risk." (PMID 31412686, 2019).
Insulin resistance (continued). "Insulin resistance has been long considered to play a key role in the development of non-alcoholic fatty liver disease (NAFLD) —which is associated with altered RBP4 levels." (PMID 30782214, 2019). "They found that the level of circulating RBP4 is linked more specifically with insulin resistance than that of other adipokines such as leptin and adiponectin." (PMID 31147589, 2019). "Genetic or pharmacologic elevation of serum RBP4 causes insulin resistance and hepatic steatosis in mice." (PMID 29114012, 2018). "RBP4 and its associated RA have been shown to trigger several downstream pathways to confer insulin resistance." (PMID 29642915, 2018). "Previous studies had suggested that circulating RBP4 levels were associated with insulin resistance, metabolic syndrome, impaired glucose tolerance, and type 2 diabetes." (PMID 30135138, 2018). "The RBP4 action is depend on its associated ligand vitamin A/retinol acid (RA) and possibly involves similar pathways as for conferring insulin resistance." (PMID 29642915, 2018). "RBP4 plays a causal role in insulin resistance by reducing immunity and inflammatory mechanisms in adipose and vascular tissues." (PMID 29495330, 2018). "Transgenic overexpression of human RBP4 or injection of recombinant RBP4 in normal mice caused insulin resistance, whereas deletion of RBP4 enhanced insulin sensitivity." (PMID 30374329, 2018). "Retinol binding protein 4 (RBP4) is one of the transport proteins for vitamin A, and its higher levels are associated with insulin resistance." (PMID 30096951, 2018). "Elevated circulating Retinol-binding protein 4 (RBP4) has been associated with insulin resistance, dyslipidemia, and hypertension." (PMID 29416053, 2018). "As RBP4 is a novel biomarker for assessing the severity of whole-body insulin resistance and associated immune-metabolic abnormalities, this robust and quantitative assay would be a useful diagnostic tool." (PMID 29416053, 2018). "Serum retinol binding protein (RBP4) is increased in insulin-resistant states and highly associated with both the magnitude of insulin resistance and individual components of the metabolic syndrome and the risk to develop coronary heart disease in humans." (PMID 29416053, 2018). "RBP4 has been shown to be associated with insulin resistance, visceral fat distribution, dyslipidemia and diabetes." (PMID 29785210, 2018). "RBP4 also had been suggested to be associated with variables related to insulin resistance and diabetic complications." (PMID 30135138, 2018). "Recently, a human study found that circulatory RBP4 and TTR is associated with glucose intolerance and obesity, and T2DM and RBP4 is associated with insulin resistance." (PMID 29747616, 2018). "The strong associations between RBP4, insulin resistance, and the percent of trunk fat in young subjects were shown to disappear in older adults." (PMID 29524177, 2018). "Animal studies suggest that transgenic overexpression of human RBP4 or injection of recombinant RBP4 in wild-type mice causes insulin resistance; on the contrary, genetic deletion of RBP4 enhances insulin sensitivity." (PMID 28931435, 2017). "RBP4 is an adipocyte-secreted molecule that is elevated in the serum seems to signal the presence of insulin resistance and associated cardiovascular risk factors." (PMID 29190912, 2017). "Increased serum RBP4 has been reported to contribute to insulin resistance associated with type 2 diabetes and obesity, which are possible risk factors for CLD progression." (PMID 26927700, 2016). "There is an established relationship between serum RBP4 levels and increased risk of metabolic syndrome of which obesity, dyslipidemia, hyperglycemia, and insulin resistance are a part." (PMID 26842399, 2016). "Conversely, transgenic overexpression of RBP4 or injections of purified RBP4 into normal mice cause insulin resistance." (PMID 25918733, 2015).